INS (insulin)
Diseases named in the same sentence as INS in open-access papers (continued):
Sharing a sentence is not in itself a finding about the gene and the disease.
diabetes (continued). "Impairment on endothelial response due to diabetes is more evident in women than in males, which alters the positive hemodynamic estrogen effects by complex interactions between insulin and estrogen signaling." (PMID 28878683, 2017). "Akita mice display severe ER stress, failure of glucose-stimulated insulin secretion in their β cells, and diabetes." (PMID 28102311, 2017). "Type 2 diabetes mellitus (T2DM) is characterized by chronic elevation of blood glucose levels because of systemic insulin resistance." (PMID 27856330, 2017). "The percentage of current and former smokers, neuropathy, CKD and commonly used medications in diabetes (e.g., insulin or/and oral glycemic medications, RAS medications) were significantly higher in DR than no DR patients." (PMID 28700742, 2017). "We agnostically studied the association of a set of inflammatory markers with progression from normoglycemia to pre-diabetes, type 2 DM and finally to insulin therapy." (PMID 28258520, 2017). "Most patients with diabetes mellitus (DM) are followed by primary care physicians, who often lack knowledge or confidence to prescribe insulin properly." (PMID 28279950, 2017). "Elimination of PAX6 activity, an epigenetic result of uterine artery occlusion induces diabetes and a dramatic reduction in the number of beta cells producing insulin in the intrauterine growth restricted rodent model." (PMID 29326659, 2017). "We highlight the complex presentation with HHS and acute pancreatitis leading to diabetes that required long term of insulin treatment." (PMID 29204299, 2017). "Lifestyle intervention studies also provide evidence for a beneficial effect of dietary fibre from wholegrains, fruit and vegetables on insulin sensitivity and reducing the risk of progression from impaired glucose tolerance (IGT) to diabetes." (PMID 29186908, 2017). "We assessed the impact of using the Accu-Chek Connect diabetes management system on treatment satisfaction, diabetes distress, and glycemic control in adults with type 1 diabetes and insulin-treated type 2 diabetes." (PMID 29027812, 2017). "The objectives of this study were to investigate the nature and prevalence of insulin-related medication discrepancies contained in hospital discharge summaries for patients with diabetes." (PMID 28852529, 2017). "As adults, women rather than men with LBW (≤2.5 kg) have higher fasting plasma glucose, insulin, diabetes, and metabolic syndrome." (PMID 28451583, 2017). "Despite the presence of beta cells in some individuals with diabetes of long duration, the insulin response to OGTT deteriorates further after type 1 diabetes becomes symptomatic, suggesting continued beta cell loss." (PMID 28550517, 2017). "A significant increase in glycated hemoglobin (+0.7% healthy group, +1.1% diabetes group), total cholesterol, low density lipoprotein, insulin, and triglycerides in the study period was also observed, suggesting an increase in dietary energy intake." (PMID 28744374, 2017). "We have confirmed the potential of IP administration of hUCWJCs to target STZ-damaged tissues, normalize hyperglycemia, promote insulin secretion from extra-pancreatic resident cells and improve renal damage typical of patients with diabetes mellitus." (PMID 29041943, 2017). "A small percentage of macrophages were shown to express NGAL and this was increased by diabetes and prevented by insulin treatment." (PMID 28182694, 2017). "Temporal changes in glycaemic traits during middle age suggest that impaired insulin secretion is a particular feature of diabetes development among South Asians." (PMID 28409212, 2017). "In the group of rats with STZ-induced diabetes, plasma insulin concentrations were below the minimum detection level in both week 2 and week 4 of the study." (PMID 29464184, 2017).
diabetes (continued). "Recent studies demonstrated that insulin signaling plays important roles in the regulation of pancreatic β cell mass, the reduction of which is known to be involved in the development of diabetes." (PMID 28886131, 2017). "It is widely accepted that adipose and muscle tissues are the major site of insulin-mediated glucose disposal due to their large contribution to body mass and serve as great modalities in diabetes studies." (PMID 29058615, 2017). "The STZ-treated animals showed the typical pathophysiological feature of diabetes, including reduction of body weight, increase of blood glucose levels, and decrease of insulin levels." (PMID 29244751, 2017). "Because ARG2 levels increase in diabetic patients and are mitigated by insulin treatment, patients with history of diabetes were excluded from the study." (PMID 28808255, 2017). "Acarbose can be an adjunct to diet and exercise as monotherapy when other oral antidiabetic agents are contraindicated, or in any combination of oral antidiabetic drugs and insulin in the management of type 2 diabetes mellitus." (PMID 28225835, 2017). "It is thus justified to conclude that replenishment of insulin-producing pancreatic β-cells is crucial for treating diabetes and its complications, thereby overcoming the inadequacies of current treatment strategies." (PMID 28576138, 2017). "Degradation of internalized insulin also improves insulin sensitivity, implicating a potential treatment of diabetes." (PMID 28070499, 2017). "Human insulin (HI) is a well-characterized natural hormone which regulates glycose levels into the blood-stream and is widely used for diabetes treatment." (PMID 28829407, 2017). "Studies on the pathophysiology of type 2 diabetes mellitus (T2DM) have linked the accumulation of lipid metabolites to the development of beta-cell dysfunction and impaired insulin secretion." (PMID 28448538, 2017). "T1DM is referred as insulin-dependent diabetes mellitus (IDDM) and is caused by the impaired production of insulin." (PMID 28770011, 2017). "The DCCT study was a comparative analysis between subjects with type 1 diabetes mellitus who received intensive insulin treatment and those receiving conventional treatment." (PMID 29089472, 2017). "Prevents diabetes in NOD mice by disrupting the pathways leading to the Th1-mediated destruction of insulin-producing beta cells." (PMID 29163443, 2017). "Compared to patients without DR, those with the condition were more likely to be male, younger, have longer duration of diabetes, use insulin, have at least one other diabetes complication, and at least one comorbidity (all p<0.05)." (PMID 28662119, 2017). "Triggering of diabetes mellitus in asthmatic patients resulted in an improvement in the asthmatic condition and treatment with insulin restored asthma symptoms." (PMID 28649241, 2017). "Only duration of diabetes was different between the two groups, with the long-acting insulin group having a longer duration of diabetes (71.5 vs 16 months, p = 0.001)." (PMID 28484424, 2017). "In contrary to the benefits of insulin therapy, significant number of patients with diabetes show low adheres to treatment and some patients avoid insulin therapy or not willing to start it." (PMID 28680863, 2017). "In model 2, after adjusting for age, sex, duration of diabetes, insulin therapy, SBP, BMI, HbA1c, and eGFR, the results were similar." (PMID 28924157, 2017). "In patients with hemochromatosis and diabetes who are presumed or known to have pancreatic siderosis, phlebotomy therapy is likely to improve insulin secretion only when hemochromatosis diagnosis and iron depletion are early." (PMID 28331855, 2017). "The agents that are used to treat diabetics by means of decreasing blood glucose concentration or sufficiently secreting insulin are known as antihyperglycemic agents." (PMID 29166935, 2017).
diabetes (continued). "A literature review revealed that available data on the use of basal insulins (including long-acting insulin analogues and neutral protamine Hagedorn [NPH] insulin) in pregnant women with diabetes come largely from retrospective studies." (PMID 28100192, 2017). "A polyclonal antibody against the mouse SeP FHR improves glucose intolerance and insulin secretion in a mouse model of diabetes." (PMID 29162828, 2017). "Investigation of confidence and approaches to delivery of diabetes care found that postgraduate medical trainees were less likely to alter oral therapy for diabetes management compared to insulin." (PMID 27896444, 2017). "Additional investigation of the role of the C18 oxylipins in obesity and other aspects of the metabolic syndrome – diabetes, insulin resistance, hepatocyte ballooning and large lipid droplets–is clearly warranted." (PMID 28970503, 2017). "At that time, the first-generation sulfonylureas (SUs) were developed as a successful oral replacement of insulin in most people with what we now know as type 2 diabetes mellitus (T2D)." (PMID 29152218, 2017). "Adiponectin has insulin-sensitizing anti-inflammation and anti-atherogenic properties, and it hence exerts a protective role in type 2 diabetes mellitus, obesity, hypertension and coronary artery disease." (PMID 28099908, 2017). "FGF21 has been considered a promising intervention target for metabolic diseases, including fatty liver, obesity, and diabetes due to its insulin-sensitizing and thermogenesis-inducing effects." (PMID 28129657, 2017). "Using these findings as a basis we can now design improved insulin analogues for the treatment of diabetes." (PMID 29222417, 2017). "Insulin has been used in the treatment of diabetes for almost a century, due to the seminal achievements in 1922 by the teams of Banting, Best, McLeod and Collip in Toronto, ON, Canada." (PMID 28798723, 2017). "The six significant gene sets were mainly observed in diabetes studies 1, 2, 3, 4, 8, 10 and 11 and insulin studies 3 and 4 (adjusted p-value < 0.05), involving tissues of adipose, arteries, blood, myotube, pancreatic tissues and skeletal muscles." (PMID 28117714, 2017). "Diabetes is an increasing and serious global health and financial problem, characterized by defective insulin secretion from the β cells of the pancreatic islets, which causes elevated blood glucose." (PMID 28954230, 2017). "A key point of discussion focused on the need for basal insulin to allow for the therapeutic benefit of glucagon blockade in the treatment of diabetes." (PMID 28323959, 2017). "Diabetes mellitus (DM) is an endocrine-based metabolic disease characterized by hyperglycemia due to insufficient insulin or/and insulin resistance (IR)." (PMID 28529539, 2017). "This form of diabetes is a consequence of the target tissues becoming resistant to the effects of insulin and the failure of pancreatic β-cells to produce enough insulin." (PMID 29026446, 2017). "GSK-3, another key signaling molecule in the insulin pathway, modulates the process of glucose metabolism and is thus a particularly intriguing candidate target for diabetes treatment." (PMID 28662169, 2017). "The three groups that developed diabetes showed distinct trajectories of fasting insulin compared with each other (all P < 0.001)." (PMID 28266592, 2017). "Type 2 DM (T2DM) is the most common form of diabetes which features insulin resistance and/or relatively reduced insulin secretion, leading to hyperglycemia and, ultimately, malfunctioning of the pancreatic β-cells." (PMID 28045446, 2017). "Specifically, Type 2 Diabetes Mellitus (T2DM) is characterized by both an insulin action resistance and a progressive dysfunction of the endogenous insulin release process." (PMID 29286314, 2017). "A variety of risk factors are related to hypoglycaemia episodes, such as increasing age, longer duration of diabetes (years since diagnosis) and complexity of insulin regimen." (PMID 28490797, 2017).
diabetes (continued). "The data presented shows the relationship between pre-existing insulin secretagogues use, adipokine profiles at the time of breast cancer (BC) diagnosis and subsequent cancer outcomes in women diagnosed with BC and type 2 diabetes mellitus (T2DM)." (PMID 27995161, 2017). "In present study, STZ injection successfully induced diabetes mellitus with defects in insulin sensitivity and secretion." (PMID 29296174, 2017). "A type 2 diabetes was induced, so insulin is still produced but some rabbits are mild diabetic while others showed severe diabetes." (PMID 28592281, 2017). "Single TCR mice expressing either insulin, chromogranin, or IGRP reactive mouse TCRs developed spontaneous diabetes, supporting the important pathogenic role for these reactivities in autoimmune diabetes." (PMID 29312143, 2017). "As such, cAMP is an attractive target for boosting insulin production particularly in diabetes therapies." (PMID 28839233, 2017). "With increased diabetes duration, the islet function diminishes gradually, resulting in reduced C-peptide and insulin levels and the prevalence of DPN increases." (PMID 28228847, 2017). "In this respect, IR-B-selective insulin analogs would be of great interest for their potential to restore more natural metabolic homeostasis in diabetes." (PMID 28798723, 2017). "Prior to the operation, 35 patients (44 %) had type 2 diabetes mellitus, nine of whom were on insulin." (PMID 27783370, 2017). "Both Impaired Fasting Glucose (IFG) and Intolerance Glucose Tolerance (IGT) which are the basis for diagnosis of pre-diabetes and diabetes result from insulin resistance (hepatic and skeletal insulin resistance, respectively) and reduced insulin secretion." (PMID 28137307, 2017). "We aimed to identify novel inflammatory markers that predict progression from normoglycemia to pre-diabetes, incident T2D and insulin therapy." (PMID 28258520, 2017). "Further, these homeostasis model indices progressively loses their importance in a patients with advancing duration of T2DM, as plasma insulin level is the numerators for these measures which progressively declines with increasing duration of diabetes." (PMID 28690682, 2017). "SF levels were positively associated with fasting glucose; impaired glucose metabolism; insulin levels; prediabetes; and diabetes in cross-sectional studies of participants unselected for hemochromatosis diagnoses." (PMID 28331855, 2017). "When IDE levels are reduced in the cytosol, incompletely degraded or inactive insulin remains in the cytosol and interferes with insulin signal transduction mechanisms resulting in insulin resistance and diabetes." (PMID 28070499, 2017). "The diagnosis of diabetes mellitus in the patients of this study was strictly defined as currently having treatments as oral medication or insulin injection." (PMID 28219351, 2017). "It is believed that ascorbic acid optimizes the islets’ insulin secretion, to facilitate impaired insulin secretion and ascorbate cycle in diabetes mellitus." (PMID 28807030, 2017). "The use of N-terminal Hsp90 inhibitors in the alleviation of diabetes related symptoms has also been investigated due to the increased levels of insulin sensitivity observed upon HSF1 activation." (PMID 29247221, 2017). "Diabetes mellitus is a metabolic disorder with chronic hyperglycaemia, which results from a defect in insulin secretion, insulin action, or both." (PMID 29086839, 2017). "The EMC-MSP drug delivery system combined the advantages of both high-storage capacity and the glucose-triggered insulin release, and had a great potential in applications for diabetes therapy." (PMID 30970930, 2017). "A total of 35 eyes of 35 patients with DME were studied; 57.15% of the patients were women, all patients had type 2 diabetes mellitus, 68.57% were treated with insulin, and the mean HbA1c was 7.9 ± 1.07% (6.3–10)." (PMID 28779336, 2017).
diabetes (continued). "The conducted studies did not indicate a relationship between the leptin concentration and the value of the glycated haemoglobin percentage in the blood of the individuals suffering from diabetes both before and after insulin therapy." (PMID 28758947, 2017). "Protein tyrosine phosphatase 1B (PTP1B) and α-glucosidase are important targets to treat obesity and diabetes, due to their deep correlation with insulin and leptin signalling, and glucose regulation." (PMID 28933230, 2017). "The five studies retrieved clearly indicate the efficacy of different therapeutic programs to improve QoL by enhancing positive diabetes self-management behaviors such as balanced diet, exercise, self-monitoring, and insulin control." (PMID 28326332, 2017). "Diabetes is a metabolic disease characterized by increased blood sugar level due to insufficiencies in insulin secretion, action, or both." (PMID 28445415, 2017). "The multivariate linear regression analysis found an interaction between the type of diabetes and insulin treatment." (PMID 29062603, 2017). "The average age was 55 (SD 11.6), 71% (5/7) were male, diabetes duration was 11 years (SD 7.3), and 71% (5/7) had been using insulin." (PMID 28554881, 2017). "Diabetes mellitus, one of the fastest growing diseases in the world, is a group of metabolic diseases characterized by hyperglycemia resulting from defects in insulin secretion, insulin action, or both." (PMID 29182587, 2017). "Type 2 diabetes mellitus (T2DM), a metabolic condition characterized by a decrease in sensitivity to endogenous insulin, is the best established environmental risk factor for the development of AD, increasing relative risk by 50%." (PMID 29312321, 2017). "Despite the high access to diabetes medications and wide insulin coverage, the current quality of national diabetes control remains subpar, compared with other areas of the world and consensus clinical targets." (PMID 29044139, 2017). "The effects of intensive insulin therapy on NMR lipoproteins were evaluated during the Diabetes Complications and Control Trial (DCCT)." (PMID 28587667, 2017). "Metformin is prescribed globally to improve insulin sensitivity, including in those individuals with Type 2 Diabetes Mellitus (DM2)." (PMID 29211738, 2017). "Research studies on adiposity and diabetes in Asian Indians have been done primarily in context of insulin secretion and insulin resistance, whereas plasma glucagon and its relation to adiposity in this ethnic group remain sparsely researched." (PMID 28634585, 2017). "Currently, there is considerable interest in targeting β cell regeneration as an effective approach to replenish insulin for patients with diabetes." (PMID 28845211, 2017). "The “perpetuum” of diabetes begins with an initial defect of insulin action followed by a decrease of beta cell function." (PMID 28468307, 2017). "In majority of the herbal products and secondary metabolites used in treating diabetes, the mechanisms of action involve regulation of insulin signaling pathways, translocation of GLUT-4 receptor and/or activation the PPARγ." (PMID 28729836, 2017). "Type 2 diabetes mellitus (T2DM) is a metabolic disorder characterized by continuous hyperglycemia associated with insulin resistance and /or reduced insulin secretion." (PMID 28693595, 2017). "Results were remarkably similar when diabetes was defined by HbA1c ≥ 6.5% (48 mmol/mol), previously diagnosed diabetes, or current use of anti-diabetic medication or insulin, supporting recent guidelines recommending HbA1c as a diabetes diagnostic tool." (PMID 29166886, 2017). "And the pharmacological agents currently approved for treatment of diabetes mellitus include sulfonylureas, metformin, acarbose, and insulin." (PMID 28386567, 2017). "The result of the peripheral blood diabetes-related miRNA regulation postoperatively was also consistent with reduction of IR, increasing glucose-induced insulin secretion, and protection of beta-cell function." (PMID 28273212, 2017).